JADE1 (jade family PHD finger 1)
Description:
Scaffold subunit of some HBO1 complexes, which have a histone H4 acetyltransferase activity. Plays a key role in HBO1 complex by directing KAT7/HBO1 specificity towards histone H4 acetylation (H4K5ac, H4K8ac and H4K12ac), regulating DNA replication initiation, regulating DNA replication initiation. May also promote acetylation of nucleosomal histone H4 by KAT5. Promotes apoptosis. May act as a renal tumor suppressor. Negatively regulates canonical Wnt signaling; at least in part, cooperates with NPHP4 in this function.
Synonyms: PHF17; JADE-1
Tractability: Antibody: its Gene Ontology location is reachable by antibodies, with high confidence. PROTAC: UniProt records ubiquitination sites on it; ubiquitination databases record sites on it.
Gene: Protein-coding gene on chromosome 4 (128,809,576 to 128,875,224, forward strand). Ensembl gene ENSG00000077684.
Subcellular location: Nucleus; Chromosome; Cytoplasm; Cytoplasm, cytoskeleton, cilium basal body
Subcellular location (Human Protein Atlas): Nucleoplasm; Centrosome
Pathways (Reactome):
Chromatin organization: HATs acetylate histones
Gene Ontology:
Molecular function: histone H3K14 acetyltransferase activity; histone H4K12 acetyltransferase activity; histone H4K16 acetyltransferase activity; histone H4K5 acetyltransferase activity; histone H4K8 acetyltransferase activity; protein binding; transcription coactivator activity; histone reader activity
Biological process: negative regulation of canonical Wnt signaling pathway; negative regulation of G1/S transition of mitotic cell cycle; regulation of cell cycle; regulation of cell growth; regulation of DNA biosynthetic process; regulation of DNA replication; regulation of DNA-templated transcription; apoptotic process; negative regulation of cell growth; chromatin organization; chromatin remodeling; positive regulation of DNA-templated transcription
Cellular component: chromosome; ciliary basal body; cytoplasm; histone acetyltransferase complex; nuclear speck; nucleoplasm; nucleus; plasma membrane
Genetic constraint (gnomAD): Loss-of-function variants: 14 observed, 78.08 expected, observed/expected ratio (o/e) 0.18, 90% interval 0.12 to 0.28. The upper end of that interval is the gene's LOEUF score, 0.28, which puts it in group 1 of 6, group 1 being the genes least tolerant of losing a copy. Missense variants: 655 observed, 1,049.3 expected, observed/expected ratio (o/e) 0.62, 90% interval 0.58 to 0.67. Synonymous variants: 342 observed, 398.61 expected, observed/expected ratio (o/e) 0.86, 90% interval 0.79 to 0.94.
Homologues: Orthologues: chimpanzee JADE1 (100% identical), macaque JADE1 (99% identical), guinea pig JADE1 (97% identical), rabbit JADE1 (97% identical), pig JADE1 (96% identical), rat Jade1 (93% identical), mouse Jade1 (92% identical), tropical clawed frog jade1 (67% identical), zebrafish jade1 (52% identical), Caenorhabditis elegans phf-15 (19% identical), Drosophila melanogaster Alh (14% identical), Caenorhabditis elegans zfp-1 (12% identical). Paralogues in human: JADE2 (45% identical), JADE3 (43% identical), BRPF3 (25% identical), BRD1 (24% identical), BRPF1 (23% identical), PHF14 (17% identical), MLLT10 (16% identical), MLLT6 (16% identical).
Diseases named in the same sentence as JADE1 in open-access papers:
JADE1 is named in the same sentence as 17 diseases in open-access papers, as found by Europe PMC text mining. Sharing a sentence is not in itself a finding about the gene and the disease. The quoted sentences say what the papers report.
renal carcinoma (6 papers, 2014 to 2023). A carcinoma arising from the epithelium of the renal parenchyma or the renal pelvis. "As another member of the JADE family JADE1 has been linked to renal cancer pathogenesis through a VHL-mutation-dependent mechanism, we next sought to determine if JADE2 mRNA was also associated with mutation of key oncogenic driver mutations in NSCLC such as KRAS or ALK." (PMID 37761019, 2023). "In addition, JADE1 was stabilized by direct interaction with pVHL and directly linked to Wnt tumorigenesis pathway in renal cancer." (PMID 34631510, 2021). "JADE1 for example, has been shown to promote apoptosis in renal cancer cells, and MUL1, which should motivate further experimental investigations." (PMID 36342924, 2022). "Nevertheless, due to its high expression in renal proximal tubules, JADE-1 has been suggested as a promising candidate for renal tumor inhibitor that accelerates the apoptosis of renal cancer." (PMID 32351328, 2020). "Within ccRCC specifically, Jade-1 expression has been shown to be prognostic for renal cancer regardless of VHL expression." (PMID 37175531, 2023). "Notably, decreased expression of JADE-1 (a major regulator of the AKT pathway) has been attributed to the poor prognosis and activation of AKT in the renal cancer cell, thus, increasing the cell invasion." (PMID 32351328, 2020).
pancreatic cancer (3 papers, 2020 to 2023). "In pancreatic cancer stem cells, Jade-1 has been implicated in the EMT phenotype through the AKT/mTOR pathway." (PMID 37175531, 2023).
acute leukemia (1 paper, 2016). A clonal (malignant) hematopoietic disorder with an acute onset, affecting the bone marrow and the peripheral blood. "In addition to BRPF1/2/3, the PZP module is found in a range of proteins that also form translocation chimeras in acute leukemias, including JADE1/2/3 and AF10/17." (PMID 26626149, 2016).
cardiac ischemia (1 paper, 2020). "In particular, the pro-apoptotic Jade1 target is predicted to be reduced in the seal heart due to high miR-499-5p, suggesting a protective mechanism against cardiac ischemia." (PMID 32293246, 2020).
chronic obstructive pulmonary disease (1 paper, 2017). A chronic and progressive lung disorder characterized by the loss of elasticity of the bronchial tree and the air sacs, destruction of the air sacs wall, thickening of the bronchial wall, and mucous accumulation in the bronchial tree. "rs116624278 is an intergenic SNP located between PGRMC2 and JADE1 genes, in a QTL for chronic obstructive pulmonary disease, heart rate and osteoarthritis." (PMID 28152013, 2017).
cleft palate (1 paper, 2021). Cleft palate is a fissure type embryopathy that affects the soft and hard palate to varying degrees. "Overexpression of miR-4680-3p inhibited cell proliferation in a dose-dependent manner through the suppression of expression of ERBB2 and JADE1, which are known cleft palate-related genes." (PMID 33585479, 2021).
non-small cell lung carcinoma (1 paper, 2025). A group of at least three distinct histological types of lung cancer, including non-small cell squamous cell carcinoma, adenocarcinoma, and large cell carcinoma. "The knockdown of JADE1 (both variants) by siRNA results in inhibition of DNA synthesis in human non-small cell lung carcinoma cell line (h1299 cells) and primary fibroblasts." (PMID 40219219, 2025).
tauopathies (1 paper, 2024). "The findings from this study indicate that PART has a genetic architecture that partly overlaps with AD and other tauopathies and suggest a novel role for JADE1 (which interacts with 0N4R tau and is protective in vivo) as a modifier of neurofibrillary degeneration." (PMID 38170841, 2024).
tumor (10 papers, 2013 to 2023). "The PHD domains in JADE1 were shown to be essential for (a) HBO1 complexes to bind chromatin and (b) for a critical JADE1-associated tumor suppressor activity, and it is important to note that the HBO1 complex has been shown to play important roles in cancer." (PMID 37761019, 2023). "The significance of Jade-1 as a tumor suppressor has previously been identified, particularly through its association with VHL." (PMID 37175531, 2023). "In light of these details, and the well supported role of AKT/mTOR in regard to EMT in ccRCC, increased scrutiny of Jade-1 as a tumor suppressor of ccRCC and a potential agent inhibiting the EMT phenotype is much needed." (PMID 37175531, 2023). "The Jade-1 protein, a growth-suppressive ubiquitin ligase, is a suspected tumor suppressor thought to regulate apoptosis and cancer cell growth and is predominantly localized in cell nuclei." (PMID 37175531, 2023). "Intriguingly, proliferative pathways typical of malignant progression are predicted to be inactivated, in particular, by JADE-1 tumor-suppressive functions through induction of apoptosis and Wnt signaling inhibition." (PMID 30943211, 2019). "In addition to its interaction with VHL, the tumor-suppressive role of Jade-1 has also been demonstrated through its regulation as a transcription factor of AKT and beta-catenin." (PMID 37175531, 2023). "In addition to known tumor-promoting genes, e.g., c-MYC, YAP1, RAD51B, TRIB3, SLC17A9, JADE1, we found that NAPRT, encoding a key enzyme for NAD+ biosynthesis from nicotinic acid, was also suppressed in HCC cells by the BRD4 inhibitor." (PMID 35399501, 2022). "Moreover, here we also attempted to unravel the mechanism by which miR-135b activate the AKT/mTOR pathway to regulate the stem cells by inhibiting JADE-1 expression, which subsequently affects the stemness of PCSCs and promotes tumor growth." (PMID 32351328, 2020). "For example, JADE1 plays a key role in HBO1 complex to regulate DNA replication initiation and, on the other hand, serves as a tumor suppressor by inhibiting proliferation and promoting apoptosis." (PMID 34631510, 2021). "Taken together, the silencing of miR-135b promotes the JADE-1 expression, which inactivates the AKT/mTOR pathway and ultimately results in inhibition of self-renewal and tumor growth of PCSCs." (PMID 32351328, 2020). "It was earlier shown that in the presence of the human tumour suppressor proteins ING4 and ING5, Jade-1 targets the chromatin through interaction with H3K4me3 modifications." (PMID 24267901, 2013). "Therefore, we concluded that inhibition of JADE-1 on the AKT/mTOR pathway affects the stemness of PCSCs and suppresses tumor growth." (PMID 32351328, 2020).
cancer (5 papers, 2020 to 2023). A tumor composed of atypical neoplastic, often pleomorphic cells that invade other tissues. "We examined the effects of Jade-1 on the cancer phenotype in ccRCC cell lines by establishing stable cell lines with a lentiviral anti-Jade-1 shRNA." (PMID 37175531, 2023). "Intriguingly, Our data from cancer cell lines and animal experiments demonstrated that miR-135b down-regulated the JADE-1 to promote proliferation and suppress apoptosis of PCSCs via the AKT/mTOR pathway." (PMID 32351328, 2020).
JADE1 also shares sentences with these, for which no sentence is quoted: prostate carcinoma (2 papers); Clear Cell Renal Cell Carcinoma (1); kidney cancer (1); lung adenocarcinoma (1); lymphoma (1); osteoarthritis (1); renal cell carcinoma (1).